ERCC1 (ERCC excision repair 1, endonuclease non-catalytic subunit)
Diseases named in the same sentence as ERCC1 in open-access papers (continued):
Sharing a sentence is not in itself a finding about the gene and the disease.
Fanconi anemia (28 papers, 2011 to 2026). Fanconi anemia (FA) is a hereditary DNA repair disorder characterized by progressive pancytopenia with bone marrow failure, variable congenital malformations and predisposition to develop hematological or solid tumors. "Presumably, exhaustion of HSCs in the Ercc1 mutant is largely caused by its replication‐associated cross‐link repair defect, as in Fanconi's anaemia (FA), in line with the notion that defects in the ERCC1 partner XPF can cause FA." (PMID 35246937, 2022). "Loss of Ercc1 causes hematopoietic defects similar to those seen in Fanconi Anemia." (PMID 22701168, 2012). "We have previously characterised the infertility defect in Ercc1−/− mice and found that Ercc1 acts together with the Fanconi Anaemia DNA repair pathway to safeguard pre-meiotic germ cell development." (PMID 38514641, 2024). "For instance, ERCC1-XPF plays an important role in the unhooking of DNA interstrand crosslinks as part of the Fanconi anemia repair pathway." (PMID 38664429, 2024). "FANCD2 is a component of the Fanconi anaemia (FA) complex, which is known to promote the loading of the ERCC1/XPF complex at ICLs." (PMID 37226898, 2023). "Among all NER proteins, ERCC1 stands out as it is also involved in Fanconi Anaemia pathway, interstrand crosslink repair and DSB repair." (PMID 33931939, 2021). "We also identified chromatin remodelers, Fanconi Anemia pathway genes, translesion DNA polymerases, and ERCC1." (PMID 25965342, 2015). "Intriguingly, analogous hypersensitivity to oxidative stress has been previously demonstrated in animal and cell culture models defective in Fanconi anemia or excision repair cross complementation group 1 (ERCC1) DNA repair pathway genes, conditions that were improved by antioxidant treatment." (PMID 37107275, 2023). "Next, we determined whether the impaired Fanconi anemia pathway disrupted by ERCC1 affected the downstream homologous recombination (HR) repair pathway in EGFR exon 19 deletion NSCLC cells." (PMID 31875360, 2020). "Importantly, the endonuclease complex Ercc1/Xpf participates in the same ICL repair pathway as the Fanconi Anemia (FA) proteins." (PMID 22701168, 2012). "Ercc1 plays an essential role not only in NER, but also in crosslink repair through the Fanconi Anemia (FA) pathway, whereas Xpg is essential for NER but does not participate in crosslink repair." (PMID 40984885, 2025). "ERCC1 is an essential protein in the NER pathway and Fanconi anemia pathway which is responsible for ICL unhooking and DNA DSB formation." (PMID 31875360, 2020). "This critical repair step requires the endonuclease XPF (FANCQ)‐ERCC1, which is recruited to the ICL by the large scaffold protein SLX4 (FANCP), and depends on the activation of the Fanconi anemia pathway by ubiquitylation of the FANCI‐FANCD2 complex." (PMID 28292785, 2017). "In the replication-dependent repair process, the Fanconi anemia pathway is activated, resulting in the ubiquitylation of FANCD2-I, followed by unhooking of one side of crosslinking DNA strands by several nucleases, such as ERCC1-XPF and MUS81." (PMID 28077981, 2017). "The Fanconi anaemia (FA) pathway constitutes a central genome maintenance system that orchestrates the repair of DNA interstrand crosslinks (ICLs) through the coordinated monoubiquitination of FANCI and FANCD2, followed by recruitment of repair effectors such as BRCA1, REV1, and ERCC1." (PMID 41486508, 2026).
bladder cancer (27 papers, 2008 to 2025). "In the ERCC1-positive group, the risk of bladder cancer (BC) recurrence and death due to BC was 30% lower." (PMID 32397531, 2020). "ERCC1 SNPs, mainly C118T (rs11615) and 17677A > C have been associated with bladder cancer occurrence and survival in several studies." (PMID 33266377, 2020). "Several studies were conducted to assess ERCC1 polymorphisms as prognostic indicators in bladder cancer." (PMID 33266377, 2020). "Extensive research has been done regarding the prognostic and predictive role of ERCC1 gene expression and polymorphisms in bladder cancer." (PMID 33266377, 2020). "Recently, several genes have been identified that are associated with bladder cancer progression and poor prognosis, such as excision repair cross-complementing group 1 (ERCC1), matrix metalloproteinase-7 (MMP-7), hyaluronidase 1 (Hyal-1)." (PMID 24223213, 2013). "In carcinogenesis, several reports discussed the relation between ERCC1 single nucleotide polymorphisms and carcinogenesis in bladder cancer only in case-control studies." (PMID 22110495, 2012). "Subsequently, we found that of the seven ERCC family genes, ERCC1, 2, 3, 5, 6, and 8 showed differential expression in bladder cancer samples." (PMID 39192988, 2024). "Protein expression of ERCC1, 2, and 5 was up-regulated in bladder cancer tissues and EGR1 was down-regulated in cancer tissues compared to normal bladder samples." (PMID 39192988, 2024). "Analyzing the previous studies, gives controversial information about predicting the prognostic role of ERCC1 in the treatment of advanced bladder cancer." (PMID 32397531, 2020). "Klatte and colleagues presented the work assessing ERCC1 as a prognostic and predictive biomarker of bladder cancer after cystectomy." (PMID 32397531, 2020). "There is a marked heterogeneity between study results assessing the predictive and prognostic role of ERCC1 in bladder cancer." (PMID 33266377, 2020). "The results of their research showed a significant relationship between a platinum-based treatment response and the ERCC1 expression in bladder cancer tissue samples (p = 0.013)." (PMID 32397531, 2020). "We aim to review all the existing literature regarding the role of the ERCC1 gene in bladder cancer and address future perspectives for its clinical application." (PMID 33266377, 2020). "The role of ERCC1 as a prognostic factor of survival was assessed in patients with advanced bladder cancer treated with platinum-based chemotherapy." (PMID 32397531, 2020). "Previous clinical studies have evaluated the predictive significance of ERCC1 for response to platinum chemotherapy, in various solid tumours (lung, colorectal, head and neck, gastric and bladder cancers." (PMID 31405143, 2019). "Accumulating studies propose ERCC1 protein expression as a prognostic and predictive biomarker for platinum resistance in various tumor entities including bladder cancer." (PMID 29445424, 2018). "Kawashima and colleagues described that ERCC1 silencing promoted sensitization to radiotherapy in bladder cancer." (PMID 29160417, 2017). "In bladder cancer, several studies have shown that ERCC1 can be a potential prognostic and/or biomarker of the efficacy of platinum-based chemotherapy." (PMID 26200905, 2015). "The gene expressions of BRCA1, MDR1, and ERCC1 were reported to be useful as markers to predict the efficacy of chemotherapy for bladder cancer patients." (PMID 24354468, 2013). "The role of ERCC1 as it relates to resistance to cisplatin was controversial in clinical studies of bladder cancer." (PMID 22110495, 2012). "In case-control studies, several reports discussed the relation between ERCC1 SNPs and carcinogenesis in bladder cancer." (PMID 22110495, 2012). "In the present study, the different prognostic values of ERCC1 according to the history of adjuvant gemcitabine plus cisplatin chemotherapy were confirmed in patients with completely resected bladder cancer." (PMID 22616552, 2012).
bladder cancer (continued). "We examined ERCC1 expression in four bladder cancer cell lines including two cisplatin-resistant cell lines." (PMID 22110495, 2012). "In accordance with these previous reports, we review the role of ERCC1 in bladder cancer from carcinogenesis to therapeutic resistance." (PMID 22110495, 2012). "Those who have bladder cancer with low ERCC1 expression are more likely to benefit from adjuvant gemcitabine plus cisplatin chemotherapy." (PMID 22616552, 2012). "We reported that of four bladder cancer cell lines, the cell line with the highest ERCC1 expression was also the most resistant to IR exposure." (PMID 22110495, 2012). "In bladder cancer, the relevance of ERCC1 expression as a biomarker selecting patients for adjuvant chemotherapy should be confirmed in further prospective studies." (PMID 22616552, 2012). "Although we did not examine Her-2 expression in our previous study, further study is needed to examine the relation between Her-2 expression and DNA repair genes, such as ERCC1, in bladder cancer." (PMID 22110495, 2012). "Further study is needed to clarify the mechanism of the relation between ERCC1 and resistance to cisplatin and IR in vitro and to discover novel CRTs for the treatment of advanced and metastatic bladder cancers." (PMID 22110495, 2012). "In our study, ERCC1 expression provided both prognostic and predictive information in patients with completely resected bladder cancer." (PMID 22616552, 2012). "In support of this we showed that down-regulation of ERCC1-XPF rendered MGH-U1 bladder cancer cells more sensitive to cisplatin." (PMID 20846399, 2010). "Garcia-Closas evaluated the influence of common genetic variation in the NER pathway on bladder cancer risk by analyzing 22 single nucleotide polymorphisms (SNP) in seven NER genes (XPC, RAD23B, ERCC1, ERCC2, ERCC4, ERCC5, and ERCC6)." (PMID 19055767, 2008). "ERCC1 has emerged as a novel biomarker of bladder cancer over the years and could be potentially targeted to maximize platinum sensitivity." (PMID 33266377, 2020). "Overall, ERCC1 expression may be exploited as both a prognostic and predictive biomarker in bladder cancer." (PMID 33266377, 2020). "Sakano suggested that, in the group of patients with bladder cancer undergoing a combined trimodality approach, the disease-specific survival might be predicted by the expression of ERCC1 and XRCC1." (PMID 32397531, 2020). "ERCC1 may predict survival in bladder cancer patients treated with platinum-based therapy and a low ERCC1 level was associated with better survival." (PMID 27626805, 2016). "Moreover, haplotype analysis revealed that cases of bladder cancer had a statistically significant excess of ERCC1-GAT haplotypes." (PMID 22110495, 2012). "We reviewed the correlation between ERCC1 and bladder cancer." (PMID 22110495, 2012). "It is controversial whether ERCC1 predicts prognosis of bladder cancer treated with cisplatin-based chemotherapy." (PMID 22110495, 2012). "In summary, we have demonstrated that ERCC1 may potentially be a novel biomarker with clinical predictive and prognostic values in completely resected bladder cancer." (PMID 22616552, 2012). "In this study, we sought to determine whether ERCC1 protein expression is an important factor in predicting the clinical outcome of completely resected bladder cancer." (PMID 22616552, 2012). "We reviewed the role of ERCC1 in bladder cancer from carcinogenesis to therapeutic resistance." (PMID 22110495, 2012). "We aimed to assess the predictive and prognostic values of excision repair cross-complementation 1 (ERCC1) in identifying appropriate patients who may potentially benefit from adjuvant chemotherapy for bladder cancer." (PMID 22616552, 2012). "The ability of ERCC1 mRNA levels in predicting response has also been shown in lung, colorectal, ovarian and bladder cancer." (PMID 20461087, 2010).
bladder cancer (continued). "Recently, several reports addressed the relation between ERCC1 expression and prognosis for cisplatin-based chemotherapy for bladder cancer, and we also reported that ERCC1 might become a good factor for predicting the efficacy of CRT for muscle-invasive bladder cancer (MIBC)." (PMID 22110495, 2012). "Therefore, ERCC1 may be an independent prognostic marker for bladder cancer." (PMID 32397531, 2020). "In bladder cancer, 3 out of these identified 39 DDR genes, i.e., SLX1A, ERCC1, and RBBP8, exhibited hypermethylation over 15%." (PMID 29445424, 2018). "Recently, we examined the prognosis of cisplatin-based neoadjuvant chemotherapy in 58 bladder cancer patients treated with M-VAC and GC therapy using the results of an immunohistochemical study of ERCC1." (PMID 22110495, 2012). "We determined the expression level and over-expressed ERCC1-XPF in TTC and down-regulated the repair proteins in bladder cancer cells." (PMID 20846399, 2010). "Low/negative expression of ERCC1 was associated with prolonged median PFS and OS in patients with bladder cancer receiving platinum-based chemotherapy." (PMID 33266377, 2020). "Thus, Use of ERCC1, MDR1, BRCA1, and Snail in combination with DYRK2 may further improve the accuracy of predicting survival in bladder cancer patients treated with neoadjuvant chemotherapy." (PMID 26087959, 2015). "In bladder cancer, ERCC1 might become an important factor to predict cisplatin resistance as in other malignancies, and our in vitro results suggested that in some bladder cancer cells, ERCC1 expression correlates with resistance to IR but not with resistance to cisplatin." (PMID 22110495, 2012). "Therefore, ERCC1 may be a potential predictive but not prognostic marker and for this reason, genetic testing could personalize chemotherapy by selecting the patients who would benefit from a platinum-based treatment in bladder cancer." (PMID 32397531, 2020). "In this study, we investigated the mRNA expression of 9 genes (XPB to XPG, ERCC1, RPA1, RPA2)involved in the NER pathway in bladder cancer tissues with/without recurrence, compared with normal bladder cancer tissue." (PMID 25535740, 2014).
melanoma (27 papers, 2014 to 2025). A malignant, usually aggressive tumor composed of atypical, neoplastic melanocytes. "Further, ERCC1 deficient melanoma cells exhibited around 10-fold more sensitivity to cisplatin than ERCC1-proficient cells and in a xenograft mouse model as well." (PMID 35463312, 2022). "Consistently, as minimum as two cisplatin treatments were sufficient to cure xenografts with deficient ERCC1, whereas ERCC1-proficient melanoma xenografts were resistant to the treatment." (PMID 34809722, 2021). "In a mouse xenograph model, ERCC1-deficient melanoma cells were also observed to be 10-fold more sensitive to cisplatin than ERCC1-proficient cells." (PMID 31405143, 2019). "Further to this, in a melanoma mouse xenograft model loss of ERCC1 resulted in sensitivity to cisplatin." (PMID 29373959, 2018). "To date, high levels of ERCC1 before platinum chemotherapy have been associated with poor response in melanoma, non-small cell lung cancer, head and neck, gastric, bladder and oesophageal cancer." (PMID 29373959, 2018). "We have previously validated ERCC1 as a therapeutic target by showing that a genetically engineered ERCC1-deficient mouse model of melanoma was uniquely sensitive to the chemotherapeutic cisplatin." (PMID 28903417, 2017). "We validated ERCC1 as a therapeutic target by showing that a genetically engineered ERCC1-deficient mouse model of melanoma was uniquely sensitive to the chemotherapeutic cisplatin." (PMID 28903417, 2017). "Increased ERCC1 expression by ERK causes cisplatin resistance in melanoma." (PMID 38438872, 2024). "In addition, the NER-associated gene ERCC1 has been reported to be an attractive target in melanoma in order to overcome cisplatin-resistance development." (PMID 30206212, 2018). "The ERCC1-deficient melanoma cells used were 10-fold more sensitive to cisplatin, leading us to conclude that biochemical inhibition of ERCC1-XPF would need to block > 90% of NER activity and achieve near 10-fold increased sensitivity to cisplatin to be of therapeutic value." (PMID 28903417, 2017). "The combination of cisplatin and DHA also proved to inhibit melanoma cell migration and to reduce the expression of the DNA‐repairing enzyme ERCC1, involved in the resistance of melanoma cells to the action of cisplatin." (PMID 40616290, 2025). "After using E-X AS7 or E-X PPI2, researchers discovered improved melanoma cell susceptibility to cisplatin, suppression of NER activity, and fewer ERCC1-XPF heterodimers in ovarian malignancy cells." (PMID 37062547, 2023). "These have also been shown to have good selectivity and potency, and sensitize melanoma cells to cisplatin, and they remain the most promising inhibitor leads developed against ERCC1/XPF so far." (PMID 36046263, 2020). "We have previously shown that ERCC1 and XPF gene expression is elevated by exposure of melanoma cells to cisplatin and that ERCC1 inactivation or inhibition renders melanoma sensitive to cisplatin." (PMID 29254481, 2017). "A semi-native western blot on native lysates from control A375 melanoma cells detected bands of ERCC1 homodimer size in two size fractions of around 80 kD." (PMID 28903417, 2017). "Our best in silico screening-derived inhibitor of the interaction between ERCC1 and XPF was active in an NER assay in melanoma cells (IC50 20 μM), but caused only a small (1.3-fold) reduction in the cisplatin IC50." (PMID 28903417, 2017). "Our previous study also indicated that ERCC1 induction by cisplatin was dependent on the MAPK pathway in melanoma cells." (PMID 29156754, 2017). "In this regard we have previously shown that cisplatin regulates the MAPK pathway to induce increased expression of DNA repair gene ERCC1 and increase melanoma chemoresistance." (PMID 29254481, 2017).